RFTN1 (raftlin, lipid raft linker 1)
Description:
Involved in protein trafficking via association with clathrin and AP2 complex. Upon bacterial lipopolysaccharide stimulation, mediates internalization of TLR4 to endosomes in dendritic cells and macrophages; and internalization of poly(I:C) to TLR3-positive endosomes in myeloid dendritic cells and epithelial cells; resulting in activation of TICAM1-mediated signaling and subsequent IFNB1 production. Involved in T-cell antigen receptor-mediated signaling by regulating tyrosine kinase LCK localization, T-cell dependent antibody production and cytokine secretion (By similarity). May regulate B-cell antigen receptor-mediated signaling. May play a pivotal role in the formation and/or maintenance of lipid rafts.
Synonyms: KIAA0084; MIG2; FLJ23866; Raftlin; PIB10; PIG9
Tractability: Antibody: UniProt places it where antibodies can reach, with high confidence; its Gene Ontology location is reachable by antibodies, with high confidence. PROTAC: ubiquitination databases record sites on it; its protein half-life has been measured.
Gene: Protein-coding gene on chromosome 3 (16,313,574 to 16,514,026, reverse strand). Ensembl gene ENSG00000131378.
Subcellular location: Cell membrane; Cytoplasm; Membrane raft; Endosome; Early endosome
Gene Ontology:
Molecular function: double-stranded RNA binding
Biological process: B cell receptor signaling pathway; dsRNA transport; membrane raft assembly; positive regulation of growth rate; response to exogenous dsRNA; toll-like receptor 3 signaling pathway; positive regulation of interleukin-17 production; protein localization to membrane raft; protein transport into membrane raft; T cell antigen processing and presentation; T cell receptor signaling pathway
Cellular component: cytoplasm; endosome; extracellular exosome; membrane raft; plasma membrane; protein-containing complex; early endosome
Genetic constraint (gnomAD): Loss-of-function variants: 23 observed, 39.55 expected, observed/expected ratio (o/e) 0.58, 90% interval 0.42 to 0.82. The upper end of that interval is the gene's LOEUF score, 0.82, which puts it in group 3 of 6, group 1 being the genes least tolerant of losing a copy. Missense variants: 649 observed, 706.82 expected, observed/expected ratio (o/e) 0.92, 90% interval 0.86 to 0.98. Synonymous variants: 248 observed, 281.02 expected, observed/expected ratio (o/e) 0.88, 90% interval 0.8 to 0.98.
Homologues: Orthologues: chimpanzee RFTN1 (99% identical), macaque RFTN1 (95% identical), guinea pig RFTN1 (76% identical), pig RFTN1 (75% identical), dog RFTN1 (72% identical), mouse Rftn1 (69% identical), rabbit RFTN1 (69% identical), rat Rftn1 (69% identical), tropical clawed frog rftn1 (46% identical), zebrafish rftn1a (27% identical). Paralogues in human: RFTN2 (26% identical).
Diseases named in the same sentence as RFTN1 in open-access papers:
RFTN1 is named in the same sentence as 20 diseases in open-access papers, as found by Europe PMC text mining. Sharing a sentence is not in itself a finding about the gene and the disease. The quoted sentences say what the papers report.
gastric cancer (2 papers, 2023 to 2024). A primary or metastatic malignant neoplasm involving the stomach. "RFTN1 is known to increase likelihood of progression in gastric cancer with higher expression leading to increased proliferation and decreased apoptosis." (PMID 39679838, 2024). "Highly expressed RFTN1 promotes gastric cancer by modulating AKT/p38 signaling pathways." (PMID 37598287, 2023).
Obesity (2 papers, 2021 to 2025). Accumulation of substantial excess body fat. "A relevant study of RFTN1 has revealed that common body mass index-associated variants confer the risk of extreme obesity." (PMID 34926685, 2021). "FTO is a known key gene associated with obesity in humans through the GWAS study and fat deposition on various animals, including pigs and cattle, whereas EFNA5 and RFTN1 are associated with meat color." (PMID 40520431, 2025).
autoimmune disease (1 paper, 2025). A disorder resulting from loss of function or tissue destruction of an organ or multiple organs, arising from humoral or cellular immune responses of the individual to their own tissue constituents. "However, since RFTN1 plays a role in immune cell signaling, it may hypothetically affect muscle function in the context of autoimmune diseases, where the immune system mistakenly attacks muscle tissue, as in myositis." (PMID 41257561, 2025).
brain tumours (1 paper, 2024). "Although not much is known about the expression of RFTN1 in brain tumours, there is information in other cancer types." (PMID 39679838, 2024).
glaucoma (1 paper, 2020). Increased pressure in the eyeball due to obstruction of the outflow of aqueous humor. "GWAS have also reported a link between ATOH7 and raftlin lipid raft linker 1 (RFTN1) and glaucoma-related optic disc parameters." (PMID 32545285, 2020).
Hyperkeratosis (1 paper, 2021). Hyperkeratosis is a histopathological term defining a thickened stratum corneum and may be present in many different skin conditions, with many possible overlaps. "The overlapping DEGs included genes associated with hyperkeratosis (upregulated LCE3E and TMEM45A), wound healing (upregulated KRT17, IL36G, TNC, and TGFBI), barrier defects (downregulated FRAS1 and BCL11A), and response to infection (upregulated IL36G, ADAP2, DFNA5, RFTN1, LITAF, and TMEM173)." (PMID 34506598, 2021).
lipid metabolic disorder (1 paper, 2023). "In our study, Rftn1 knockdown induced the destruction of lipid rafts structures and lipid metabolic disorder, inducing the activation of various proinflammatory responses." (PMID 37635214, 2023).
ovarian carcinoma (1 paper, 2011). A malignant neoplasm originating from the surface ovarian epithelium. "RFTN1 is located on chromosome 3p24, a region shown to be frequently deleted in ovarian cancer, including in OV90 cells." (PMID 22141344, 2011).
renal carcinoma (1 paper, 2024). A carcinoma arising from the epithelium of the renal parenchyma or the renal pelvis. "Increased RFTN1 expression is noted to be a negative prognostic factor in renal cancers." (PMID 39679838, 2024).
salmonellosis (1 paper, 2012). Infections with bacteria of the genus salmonella. "The role of this immune pathway in resistance to salmonellosis is strengthened by the detection in chromosome 2 of RFTN1, which modulates T cell receptor signals and which is necessary for the fine-tuning of T cell-mediated immune responses and especially the Th17 immune response." (PMID 22613937, 2012).
skin cancer (1 paper, 2024). "RFTN1 expression is increased in skin cancer development as well." (PMID 39679838, 2024).
ulcerative colitis (1 paper, 2023). An inflammatory bowel disease involving the mucosal surface of the large intestine and rectum. "Next, we investigated RFTN1 expression in ulcerative colitis (UC) patients." (PMID 37591835, 2023).
infection (3 papers, 2020 to 2023). The state of being infected such as from the introduction of a foreign agent such as serum, vaccine, antigenic substance or organism. "To verify the necessity of norharman-increased H3K9/14ac binding at the promoter of Rftn1, we used substitution promoters by infection with Rftn1 lentiviral vectors." (PMID 37635214, 2023). "In addition, several DEGs, including IL36G, ADAP2, DFNA5, RFTN1, LITAF, and TMEM173, that were commonly upregulated in the partial sets of the epithelium and mucosa are associated with the response to infection." (PMID 34506598, 2021).
cancer (2 papers, 2020 to 2024). A tumor composed of atypical neoplastic, often pleomorphic cells that invade other tissues. "Among nine candidate oncogenes, high expression of four genes including RFTN1, HMGB1, RPL24, and RPL31 were reported to be correlated with a poorer prognosis in cancers (conversely, one may say that low expression of such genes shows good prognosis)." (PMID 32039517, 2020).
tumor (2 papers, 2023 to 2024). "Overactive T cells from increased RFTN1 expression within the brain could lead to neuroinflammation and may cause altered immune regulation as well as increased proliferation and decreased apoptosis of tumour cells." (PMID 39679838, 2024).
kidney disease (1 paper, 2023). "Interestingly, our analysis identified several previously unidentified CpG sites associated with baseline eGFR with nearby genes having differential expression between samples from people with and without kidney disease, such as RFTN1 and CTSB (“Discussion”)." (PMID 37188670, 2023).
metabolic disorders (1 paper, 2021). "Our findings indicated that the downregulation of LINC00690 and the upregulation of RFTN1 played a key role in the metabolic disorders of PDC." (PMID 34926685, 2021).
RFTN1 also shares sentences with these, for which no sentence is quoted: Crohn disease (1 paper); keloid (1); myositis (1).